IL6 (interleukin 6)
Diseases named in the same sentence as IL6 in open-access papers (continued):
Sharing a sentence is not in itself a finding about the gene and the disease.
Obesity (continued). "Adipose tissue, rather than muscle, is considered the primary source of chronically elevated circulating IL-6 and other pro-inflammatory factors (e.g., TNF-a) levels in obesity." (PMID 40171198, 2025). "We found that the levels of TNF-α in experimental obesity-related SAP were higher than IL-1β, IL-6, and IFN-γ, indicating its potential unique role." (PMID 39856555, 2025). "Recent studies have highlighted the interplay between IL-6, STAT3, and NF-κB signaling pathways in adipocytes, particularly in the context of obesity-induced inflammation." (PMID 41463063, 2025). "Obesity can skew the adipose tissue to secrete adipokines, including MCP-1, TNF-α, IL-1β, and IL-6, which perpetuate a low-grade inflammation or meta-inflammation." (PMID 41472730, 2025). "Shift from M1 to M2 Macrophages: In obesity, adipose tissue is characterized by an infiltration of proinflammatory M1 macrophages, which secrete cytokines such as TNF-α and IL-6, contributing to systemic inflammation and insulin resistance." (PMID 40863154, 2025). "MMe were first described as an obesity-induced ATM state in adipose depots driven by saturated free fatty acids and NOX2-dependent metabolic activation that secretes IL-6 and promotes cancer stem-like properties via GP130/STAT3 signaling." (PMID 41310829, 2025). "Interleukin‐6 (IL‐6), tumor necrosis factor alpha (TNF‐α), and irisin (cytokines) are affected by excess body fat (obesity), skeletal muscle, and resistance exercise (RE)." (PMID 40243109, 2025). "Higher mean levels of IL-6 and CRP were observed in the BMI ≥ 25 group, indicating an elevated inflammatory response in individuals with overweight or obesity." (PMID 40944273, 2025). "Adiponectin release is inhibited by pro-inflammatory cytokines such as IL-6 released from PVAT, and PVAT-derived adiponectin is reduced in obesity." (PMID 40137085, 2025). "In obesity, increased infiltration of immune cells—particularly M1 macrophages and Th1/Tc1 lymphocytes—promotes the release of cytokines such as TNF-α, IL-6, and MCP-1." (PMID 41302933, 2025). "Together with the increases in HDL cholesterol and IL-10 and the reductions in LDL cholesterol and IL-6, these adaptations highlight the comprehensive cardiometabolic and anti-inflammatory benefits of web-based HIIT in middle-aged men with obesity." (PMID 41367390, 2025). "The authors applaud the results of a clinical study in which clinical periodontal inflammatory parameters and whole salivary IL-6 and IL-1β were significantly higher among patients with class II and III obesity than patients with class I obesity." (PMID 41396032, 2025). "It is known that VF releases proinflammatory cytokines, such as TNF-α and IL-6, which increase bone resorption, decreases BMD, and it was shown that postmenopausal women with obesity who also have visceral adiposity have lower osteocalcin levels." (PMID 40854969, 2025). "By secreting inflammatory molecules such as IL-6, IL-1β, and TNF-α, macrophages drive inflammation, exacerbating obesity, insulin resistance, and type 2 diabetes." (PMID 40453651, 2025). "It is an important phenotype of obesity characterized by increased levels of proinflammatory cytokines, such as TNF‐α, IFN‐γ, IL‐1β, and IL‐6." (PMID 39968210, 2025). "Exercise interventions (aerobic, resistance, and combined training) can significantly reduce obesity indicators including WC, BMI, and BF%, while lowering levels of inflammatory markers such as CRP, TNF-α, and IL-6." (PMID 41561801, 2025). "Both IL-6 and TNF-α are elevated in obesity and metabolic syndrome and can induce insulin resistance by disrupting insulin signaling pathways." (PMID 40722699, 2025). "Individuals exhibiting frailty often display elevated levels of Interleukin-6 (IL-6), C-reactive protein (CRP), and Tumor Necrosis Factor-alpha (TNF-α), partially attributed to the prevalence of overweight/obesity in the elderly population." (PMID 40413725, 2025).
Obesity (continued). "Research has shown elevated serum levels of IL-6 and TNF-α in both diabetes and obesity, with IL-6 and C-reactive protein (CRP) levels predicting the future onset of type 2 diabetes." (PMID 39852378, 2025). "By incorporating adiposity, TyG-BMI captures obesity’s contribution to IR—through pro-inflammatory adipokines (e.g., TNF-α, IL-6) and reduced adiponectin—amplifying systemic inflammation and metabolic dysfunction." (PMID 41141345, 2025). "Therefore, the observed combination of elevated ferritin and reduced serum iron levels in our MetS + and obesity groups is mainly driven by obesity-associated low-grade inflammation and the consequent activation of the IL-6–hepcidin axis, rather than by other inflammatory conditions." (PMID 40332421, 2025). "Obesity is characterized by chronic low-grade inflammation driven by excessive adipose tissue, which secretes pro-inflammatory cytokines such as TNF-α and IL-6, thereby impairing insulin signaling and inducing insulin resistance." (PMID 41153828, 2025). "IL-6 and Hs-CRP are well-known indicators of inflammation, and their elevated levels in obese children suggest that obesity is not only a result of poor diet and inactivity but also an inflammatory condition." (PMID 40641901, 2025). "Obesity-related cytokines such as TNF-α and IL-6 stimulate tissue factor expression in endothelial cells and monocytes." (PMID 40871683, 2025). "In contrast, obesity induces a phenotypic switch toward the pro-inflammatory M1 subtype, characterized by the release of TNF-α, IL-6, and IL-1β, which exacerbates adipose inflammation and contributes to systemic insulin resistance." (PMID 41310829, 2025). "This inflammatory response increases the secretion of proinflammatory cytokines, including tumor necrosis factor (TNF), interleukin-6 (IL-6), and leptin, while levels of insulin-like growth factor-1 (IGF-1) typically decrease with age and obesity." (PMID 41156491, 2025). "In obesity, however, APC differentiation is dysregulated by increased exposure to pro-inflammatory cytokines (e.g., TNF-α, IL-6) and fibrotic signals, such as transforming growth factor-beta (TGF-β)." (PMID 40699742, 2025). "In conditions associated with inflammation (a common occurrence in cases of obesity and insulin resistance), the reduction in inflammatory cytokines (e.g., TNF-α, IL-6) that hinder insulin action can be attributed to SCFA production." (PMID 40650200, 2025). "We also found that diet-induced obesity increased the secretion of tumor necrosis factor-α (TNF-α), interleukin-6 (IL-6), and galectin-3." (PMID 40565066, 2025). "Obesity is strongly correlated with inflammatory biomarkers, such as CRP, interleukin‐6 (IL‐6), and tumor necrosis factor‐alpha (TNF‐α), both IL‐6 and TNF‐α are produced by adipocytes and act as adipokines and inflammatory markers." (PMID 40551726, 2025). "In obesity, pro-inflammatory adipokines such as tumor necrosis factor (TNF) and interleukin-6 (IL-6) are upregulated in adipose tissue, triggering chronic low-grade inflammation that impairs systemic metabolic regulation." (PMID 40703156, 2025). "miR-130a-3p which also plays a cardioprotective role by reducing TNF-α, IL-6, VCAM-1, ICAM-1 and E-selectin expression is downregulated by hyperglycemia and obesity." (PMID 40696355, 2025). "This pro-inflammatory state and cell imbalance observed in patients with obesity is the consequence of an increased production of adipokines, such as tumor necrosis factor alpha (TNF-a), interleukin-6 (IL-6), and C-reactive protein (CRP), by the adipocytes." (PMID 40435018, 2025). "Relevant meta-analyses emphasize the pivotal role of overweight or obesity in CA risk and elucidate that a high-fat diet may lead to an increase in circulating fatty acids, subsequently triggering inflammation and releasing TNF-α and IL-6, thereby promoting CA development." (PMID 38846540, 2024).
Obesity (continued). "The current study evaluated the association between IH, low ferritin and inflammation parameters (interleukin 6 (IL-6), C-reactive protein (CRP), human chorionic gonadotrophin (hCG) and obesity." (PMID 38330593, 2024). "In C57BL/6J (B6) obese mice induced by genetic obesity (db/db) and high-fat and high-sugar diet, nicotine inhibited the increase of F4/80 in obesity-induced inflammation and the levels of proinflammatory cytokines such as TNF-α, IL-6, IL-1β and iNOS in serum." (PMID 38681197, 2024). "This study aims to investigate the effects of low-fat diet on liver enzymes and serum levels of inflammatory cytokines such as chemerin, IL-6, TNF-α, and myokines such as irisin, FGF-21 in individuals with overweight, obesity and NAFLD." (PMID 38608067, 2024). "According to existing research, obesity induces chronic low-grade inflammation, marked by increased secretion of inflammatory molecules like TNF-α, IL-6, and monocyte chemoattractant protein-1 (MCP-1), primarily by visceral adipose tissue." (PMID 39376657, 2024). "Obesity triggers immune dysfunction characterized by the release of inflammatory adipokines such as TNF-α, IL6, and leptin from adipose tissues." (PMID 38474087, 2024). "An augmentation in obesity and adipose tissue mass correlates with elevated concentrations of pro-inflammatory cytokines, including TNF-α and IL-6." (PMID 39742290, 2024). "The association between obesity and inflammatory parameters was verified, and it was observed that obesity groups 1 and 2 presented elevations in plasma concentrations of TNF-α and IL-6." (PMID 39408365, 2024). "Sixty minutes of MICE increased IL‐6 and irisin concentrations while suppressed NPY and appetite perceptions in males with obesity." (PMID 39722170, 2024). "Regarding the correlation analyses of RAS components with hepatic cytokines in individuals with obesity and MASLD, a significant positive correlation was observed between ACE, and all analyzed cytokines (TNF-α, IL-6, IL-4, IL-13, IL-10)." (PMID 39337863, 2024). "Alongside possible reduced iron absorption, some inflammatory markers are reported to be increased in obesity including C-reactive protein (CRP), IL-6, and ferritin." (PMID 39236809, 2024). "Modulation by pro-inflammatory cytokines such as interleukin (IL-6) and tumor necrosis factor-alpha (TNF-α), as well as anti-inflammatory drugs, suggests that nesfatin plays a role in obesity and inflammation." (PMID 39455994, 2024). "Obesity leads to the release of pro-inflammatory substances like tumor necrosis factor alpha (TNF-α), interleukin-6 (IL-6), and C-reactive protein (CRP), which induce the generation of ROS, resulting in elevated oxidative stress." (PMID 39194738, 2024). "Our data represent a TNF-α/stearate cooperativity model driving IL-6 expression in 3T3-L1 cells via the H3K9/18Ac-dependent mechanism, with implications for adipose IL-6 exacerbations in obesity." (PMID 38928498, 2024). "Obesity is believed to induce a state of chronic inflammation due to adipose tissue releasing pro-inflammatory cytokines such as TNF and IL-6." (PMID 39335469, 2024). "What is the functional outcome of targeting IL-6 trans-signaling in the presence of other cytokines (IL-1β, TNF-α, and IL-18) in obesity?" (PMID 39125976, 2024). "Serum proteome analysis revealed the effects of the infection on circulating adiponectin, interleukin 6 (IL-6), and carbonic anhydrase 5A (CA5A), which are all related to obesity and blood glucose abnormalities." (PMID 38474155, 2024). "In a fructose-induced obesity model, SPX injection was found to significantly reduce the levels of pro-inflammatory cytokines (TNF-α, IL-1β, and IL-6) in the epididymal adipose tissue of mice." (PMID 38234666, 2024). "The secretion of inflammatory cytokines such as IL-6 and TNF-α is increased in patients with obesity." (PMID 39199353, 2024).
Obesity (continued). "In obesity, the increase in adipocyte size is related to the increased release of pro-inflammatory adipocytokines such as tumor necrosis factor (TNF) and interleukin-6 (IL-6)." (PMID 38601207, 2024). "Previous studies have highlighted the role of pro-inflammatory cytokines, such as IL-6 and TNF-α, as critical mediators in developing insulin resistance and obesity-induced inflammation." (PMID 39513912, 2024). "In consistent with obtained results regarding reduction of pre-inflammatory changes in obesity, suppressing an decreasing of TNF-α and IL-6 production in adipose tissue or serum, reducing IL-β1." (PMID 38504163, 2024). "In obesity, inflamed and dysfunctional adipocytes within WAT release pro-inflammatory cytokines (TNF-α, IL-6, IL-8, and MCP-1) and attract immune cells such as macrophages, mast cells, and lymphocytes, further amplifying the immune response." (PMID 40474934, 2024). "Previous studies have demonstrated the anti-inflammatory activity of CLA, which blunts cytokine release in adipose tissues by inhibiting obesity-induced TNF-α and IL-6." (PMID 38317220, 2024). "In the state of obesity, adipose tissue releases various chemokines and inflammatory factors, including MCP-1, TNF-α, IL-1β, and IL-6." (PMID 39334887, 2024). "Obesity is a chronic, low-grade inflammatory condition characterized by the release of pro-inflammatory cytokines from adipose tissue, including TNF-α, IL-6, and IL-17, which can impact treatment outcomes." (PMID 39768570, 2024). "Monocytes of lean people and people with obesity were activated with LPS for 4 hours to analyze TNF release or 16 hours to analyze IL-1ß, IL-6, and IL-8 release, and cytokine concentrations were analyzed in the supernatant." (PMID 39050851, 2024). "Obesity is related to chronic low-grade inflammation, with the production of proinflammatory adipokines, such as tumor necrosis factor-α (TNF-α), interleukin-6 (IL-6), leptin, monocyte chemoattractant protein-1 (MCP-1), and resistin." (PMID 38542788, 2024). "After 3 months, reductions in TNF-α, IL-6, and FGF-21 levels were significant in individuals with obesity/overweight and NAFLD." (PMID 38608067, 2024). "Dysfunctional endothelial cells release more IL-6, TNF-α, and PAI-1 and VWF, which induce highly inflammatory and procoagulant states in patients with obesity." (PMID 39199353, 2024). "In obesity, chronic systemic low-grade inflammation is triggered by the release of numerous inflammatory factors, including TNF-α and IL-6, which can activate NF-κB pathway." (PMID 38453770, 2024). "In pregnant women, both obesity and diabetes increase pro-inflammatory cytokines and adipokines, such as TNF-α, IL-6, IL-1β, leptin, and resistin, which are involved in the inflammatory response." (PMID 39584800, 2024). "Higher levels of IL-6 and TNF-α in obesity lead to increased osteoclastogenesis and bone resorption." (PMID 38892923, 2024). "Seymour and co-workers reported, in obesity-prone rats fed with an HFD, that the intake of tart cherries reduced retroperitoneal IL-6 and TNF-α mRNA expression, Nuclear factor kappa B (NF-κB) activity, and plasma IL-6 and TNF-α concentrations." (PMID 38671836, 2024). "The presence of inflammatory cytokines, including elevation in serum levels of IL-6 and TNF-ά, has been demonstrated in diabetes and obesity." (PMID 39513912, 2024). "Excess adipose tissue/obesity results in an increased release of various ‘adipocytokines’ like leptin, resistin, tumor necrosis factor-alpha (TNF-α) and interleukin-6 (IL-6)." (PMID 38791525, 2024). "An increased secretion of IL-6, leptin, IGF-1, and TNFα in obesity promotes EMT and inflammation, and dampens the immune response." (PMID 38248845, 2024). "A positive and significant correlation was found between IL-6 and BMI in Egyptian adults with grade III obesity, using approximately the same inclusion criteria as ours." (PMID 38257150, 2024).
Obesity (continued). "Investigation of the inflammatory status of BAT documented an increase in immune responses in HFD-induced obesity conditions relative to some of the inflammatory markers tested here, such as TNF-α, IL-1β, and IL-6 cytokines." (PMID 38671836, 2024). "The downregulation of PD-L1 is influenced by the inflammatory cytokines prevalent in obesity, such as TNF-α and IL-6, which can directly impact PD-L1 expression and function." (PMID 40729297, 2024). "As a pro-inflammatory state, Obesity is characterized by elevated levels of inflammatory cytokines such as TNF-alpha, IL-6, and CRP." (PMID 39829729, 2024). "Psoriasis and obesity share some cytokines with proinflammatory activity, like TNF-α, IL-1, and IL-6 and some adipokines (i.e., adiponectin, leptin, resistin, or lipocalin) with a pathogenic role in both diseases." (PMID 39062334, 2024). "IL-6 is predominantly produced by infiltrated adipose tissue macrophages, while elevated MMP-2 and MMP-9 levels in obesity contribute to adipose tissue remodeling, triggering proinflammatory cytokine secretion and amplifying the inflammatory response." (PMID 38495901, 2024). "For example, the significance of TNF-α in obesity and NAFLD, as well as IL-6 in diabetes has been reported." (PMID 38504163, 2024). "Obesity is a systemic chronic metabolic inflammation, with upregulation of inflammatory markers such as tumor necrosis factor (TNF-α), interleukins (IL)-6, IL-1β, and CCL2 in the adipose tissue of obese individuals." (PMID 39050542, 2024). "Meanwhile, in obesity, saturated fatty acids induce the ATM to polarize to an M1 phenotype, producing IL-6, TNF-α, IL-12, and IL-1β, among other inflammatory factors contributing to the impairment of insulin signaling and promoting IR." (PMID 38610754, 2024). "Obesity leads to an increased systemic inflammation, during which adipocytes release pro-inflammatory cytokines such as TNF-α, IL-6, and C-reactive protein." (PMID 39839130, 2024). "In conditions of chronic inflammation, such as obesity, IKKβ is activated by pro-inflammatory cytokines like TNF-α (tumor necrosis factor-alpha) and IL-6 (interleukin-6)." (PMID 38920999, 2024). "First, naps >30 min increase nocturnal sleep fragmentation and the frequency of awakenings, leading to elevated IL-6 and CRP levels, which then increase the risks of inflammation and obesity." (PMID 38590820, 2024). "Our study revealed that a 6-month curcumin treatment significantly reduced IL-1β, IL-6, and TNF-α in type 2 diabetes patients with obesity." (PMID 39125322, 2024). "Both psoriasis and obesity induce the production of inflammatory markers and mediators, such as TNF-α, and produce pro-inflammatory cytokines, including C-reactive protein and IL-6." (PMID 39200092, 2024). "Adipocytes also contribute to the development of obesity-induced inflammation by increasing the secretion of MCP-1, TNF-α, and IL-6." (PMID 39609876, 2024). "Among the most well-studied cytokines concerning obesity are the inflammatory cytokines such as TNF-α (tumor necrosis factor alpha), interleukin-6 (IL-6), and the anti-inflammatory cytokine IL-10." (PMID 39180618, 2024). "In AT of people with obesity, the secretion of cytokines such as TNF-α and IL-6 is upregulated, which stimulates the hepatic release of acute-phase proteins such as C-reactive protein (CRP)." (PMID 38474344, 2024). "Macrophage polarization is one of the steps of the inflammatory reaction in obesity and is crucial for the secretion of pro-inflammatory mediators such as TNF-α, IL-6, and MCP-1." (PMID 39063610, 2024). "In participants with obesity, we observed significantly elevated inflammatory marker (TNF-α and IL-6), myeloperoxidase, leptin, and insulin levels (p < 0.05)." (PMID 39700087, 2024).